TSHR (thyroid stimulating hormone receptor)
Diseases named in the same sentence as TSHR in open-access papers (continued):
Sharing a sentence is not in itself a finding about the gene and the disease.
thyroid cancer (continued). "Nevertheless, a recent meta-analysis showed that CTCs expressing thyroid-stimulating hormone receptor (TSHR), rather than EpCAM, are a reliable marker for the diagnosis of patients with thyroid cancer recurrence or metastasis." (PMID 40095491, 2025). "The authors observed that when these mice were crossed with TSH receptor gene knockout TSHR−/− mice, and these mice did not develop thyroid cancer." (PMID 28117293, 2017). "It was found that luteolin could inhibit the growth of thyroid cancer cells by reducing BRAF-activated non-protein coding RNA (BANCR) and thyroid stimulating hormone receptor (TSHR)." (PMID 40098621, 2025). "Thyroid carcinoma cells often do not express thyroid-specific genes including sodium iodide symporter (NIS), thyroperoxidase (TPO), thyroglobulin (TG), and thyrotropin-stimulating hormone receptor (TSHR)." (PMID 18682709, 2008).
hypothyroidism (110 papers, 2005 to 2025). Abnormally low levels of thyroid hormone. "In comparison, pLoF variants in NFATC1 (MAF < 0.001%—OR = 4.36, 95% CI = 2.11–8.99, P = 6.7 × 10−5) were associated with higher effect compared to TSHR pLoF variants, suggesting a potential monogenic role in hypothyroidism." (PMID 41238958, 2025). "pLoF variants in TSHR, an established monogenic cause of hypothyroidism, were associated with increased disease risk (MAF < 1%—OR = 3.02, 95% CI = 2.25–4.06, P = 2.5 × 10−13)." (PMID 41238958, 2025). "TSHR mutations result in wide spectrum of clinical manifestations, ranging from mild to severe hypothyroidism and hyperthyroidism." (PMID 41393297, 2025). "In our screening of patients in the FinnGen database with nonautoimmune congenital hypothyroidism, TSH resistance, or rare TSHR variants linked to hypothyroidism, we identified both what we believe to be novel and previously known TSHR mutations." (PMID 38194289, 2024). "The TSHR loss-of-function mutation contributes to blocking TSH action to increase TSH levels to induce hypothyroidism with thyroid hypoplasia." (PMID 37686882, 2023). "TSHR KO mice are normal at birth and human fetuses harboring mutations in the TSHR are of normal size at birth but develop hypothyroidism and have a smaller thyroid." (PMID 34249923, 2021). "C.RF-Tshrhyt/hyt mice (Tshrhyt/hyt mice) represent another model of hypothyroidism resulting from a TSHR mutation in the fourth transmembrane domain." (PMID 22916127, 2012). "C.RF-Tshrhyt/hyt mice have a mutated thyroid stimulating hormone receptor (P556L-TSHR) and these mice develop severe hypothyroidism." (PMID 22916127, 2012). "The molecular mechanism underlying TKI-induced hypothyroidism may involve suppression of thyroid-stimulating hormone receptor (TSHR) expression through the p-ERK/p-AKT–c-Myc signaling axis, leading to thyroid dysfunction." (PMID 41246328, 2025). "TSHR loss-of-function mutations and wide spectrum of hypothyroidism phenotype." (PMID 38194289, 2024). "Mutations in the TSHR gene results from loss or gain of function of the protein that causes different phenotypic variations and lead to hyperthyrotopinemia to severe Congenital Hypothyroidism." (PMID 37561783, 2023). "Beside the observed variants in RNPC3, we found another variant in TSHR (c.154C>A) that might be linked to hypothyroidism status seen in the affected members of the studied family (IV-2 to IV-5)." (PMID 37680843, 2023). "Additional thyrotropin receptor (TSHR) antibodies that block TSH function can cause hypothyroidism." (PMID 36003348, 2022). "Findings of thyroid follicular cell atrophy were considered directly related to the action of K1-70TM causing hypothyroidism via effective blocking of TSHR stimulation by TSH and were consistent with the low thyroid hormone levels recorded in the study animals." (PMID 32257067, 2019). "In the present study, TSHR variations mainly present with severe hypothyroidism, while DUOX2 variations were less common." (PMID 41133710, 2025). "In humans, our previous research demonstrated that OMC exposure disrupted vascular homeostasis in pregnant women with hypothyroidism, potentially involving TSHR and TRα1, as indicated by docking studies." (PMID 41471385, 2025). "Loss-of-function mutations in TSHR lead to variable degrees of TSH resistance, presenting with severe CH to subclinical hypothyroidism with mildly elevated TSH." (PMID 38194289, 2024). "Therefore, the TSHR mutation may be mainly linked to hypothyroidism risk in Asians." (PMID 37686882, 2023). "WES analysis showed several variants in genes associated with short stature, GH deficiency and hypothyroidism including ACAN, GHR, RNPC3 and TSHR (Table-II)." (PMID 37680843, 2023). "Both hyper‐ and hypothyroidism activate TSHR through TSHR‐Ab and TSH, respectively, thereby inducing an increased expression of thyroid/orbital antigens and worsening of autoimmune reactions directed against them." (PMID 35604323, 2022).
hypothyroidism (continued). "The TSHR-KO mouse is a good model of hypothyroidism which is useful for studying treatment protocols to correct the deficit." (PMID 34276566, 2021). "In the state of hypothyroidism, TSHR null mice were severely runted and wasted during the pre-weaning period and died within one-week post-weaning." (PMID 34440752, 2021). "In AT patients, TRAbs bind to TSHR without activating it and prevent the combination of TSH and TSHR, resulting in hypothyroidism." (PMID 33144894, 2020). "These factors include high titer of TSHR-Abs and the development of hypothyroidism after the treatment with 131I." (PMID 31929534, 2020). "Th1-cell-mediated autoimmunity leads to thyroid cell apoptosis and hypothyroidism in HT while a hyperreactive Th2-mediated humoral response against TSHR with stimulatory antibodies results in GD thyrotoxicosis." (PMID 27340576, 2016). "In order to clarify the mechanisms of hypothyroidism in Tshrhyt/wild mice, we studied the effects of TSHR(M) on the function(s) of wild-type TSHR (TSHR(W))." (PMID 22916127, 2012). "As heterozygotic TSHR KO mice are unaffected and maintain a euthyroid state, the evidence prompted us to study the reasons why Tshrhyt/wild mice exhibit hypothyroidism." (PMID 22916127, 2012). "The balance between T3 production (stimulated by TSH and by TSHR stimulating autoantibodies and suppressed by TSHR blocking autoantibodies) and T3 degradation, dictates whether hypothyroidism in GD progresses or resolves." (PMID 40416990, 2025). "The one situation where the biological assessment of TSHR blocking antibodies may be justified is in pregnancy where neonatal hypothyroidism has been reported secondary to maternal blocking antibody but this has proven to be a very rare occurrence." (PMID 35909553, 2022). "Previous studies have shown that chromosome 14 is associated with thyroid disorders; particularly hypothyroidism and its most important gene-regions are 35 Mbp, 95 Mbp and 93 Mbp, in close proximity to the rs2268458 SNP15–18, which is located on intron 1 of TSHR gene." (PMID 36130976, 2022). "Occasional patients with GO may present with active inflammatory eye disease in the presence of hypothyroidism and high titers of TRAb antibodies, which contain a proportion of TSHR-blocking antibodies." (PMID 32845332, 2020). "For instance, we found two different missense variants in TSHR that were both associated with hypothyroidism independent of the PTV association." (PMID 29691392, 2018). "In this study, TSHR mutant mice were fed L-thyroxine powder after weaning and exhibited the same T4 level as wildtype mice in adulthood, suggesting that the difference in their phenotype could be excluded by thyroid insufficiency." (PMID 31179344, 2019). "BALB/c mice immunized with the TSHR A-subunit plasmid developed TSHR/insulin-like growth factor 1 receptor (IGF-1R) antibodies, hypothyroidism, orbital inflammation, and proptosis, mimicking TAO." (PMID 40605078, 2025). "Additional TSH receptor (TSHR) antibodies block the function of TSH, which can lead to hypothyroidism." (PMID 40270696, 2025). "Contrary, TSHR-blocking antibodies (TBAb) act as antagonists, which block the action of the TSH, leading to the HT hypothyroidism." (PMID 34981746, 2022). "Mice lacking the TSHR gene (TSHR-/-) exhibit severe developmental and growth retardation, profound hypothyroidism, and severe osteoporosis, characterized by undetectable serum T3 and T4 levels but elevated TSH." (PMID 41393297, 2025). "Lack of TSH or its action due to mutations inactivating the TSH receptor (TSHR) impairs thyroid function, leading to hypothyroidism." (PMID 38194289, 2024). "Since these compounds do not affect the basal activity of TSHR, this avoids the development of hypothyroidism, one of the undesirable effects when using allosteric inverse agonists of TSHR." (PMID 37047169, 2023).
hypothyroidism (continued). "Consequently, TSHR mutations along with DIO2 T92A SNP (“double hit”) may lead to a significant reduction in DIO2 activity stimulated by TSH, and thereby may have clinical relevance in a select population of hypothyroidism patients who might benefit from a T3/T4 combination therapy." (PMID 29973617, 2018). "In such case, ichthyosis and hypothyroidism could be co-inherited, since the TGM1 and TSHR genes maps to the same chromosome localization (14q)." (PMID 23192619, 2013). "TSHR knockout (TSHR-KO) mice have small thyroid glands, and show severe hypothyroidism with no detectable thyroid hormone and elevated TSH." (PMID 22916127, 2012). "Only a minor number of GD patients develop hypothyroidism due to the TSHR-blocking antibodies." (PMID 34981746, 2022). "During DMF treatment, one female patient developed mild hypothyroidism with negative anti-TPO, anti-Tg and anti-TSHR autoantibodies; her serum TSH level then normalized spontaneously." (PMID 35624879, 2022).
autoimmune thyroid disease (100 papers, 2010 to 2025). Inflammatory disease of the thyroid gland due to autoimmune responses leading to lymphocytic infiltration of the gland. "Thyroid-associated ophthalmopathy (TAO) is a chronic inflammatory orbital disorder strongly linked to autoimmune thyroid diseases, driven by cross-reactive immune responses targeting shared antigens, such as the thyrotropin receptor (TSHR)." (PMID 41306495, 2025). "Variation at the TSHR locus has also been associated with altered lipid and bone metabolism and autoimmune thyroid diseases." (PMID 38194289, 2024). "To date, studies aimed to unveil the mechanistic role of TSHR intron 1 variants in gene function and thyroid autoimmunity pointed to two distinct mechanisms." (PMID 28421036, 2017). "We would also underline that in one patient, thyroid autoimmunity was only revealed by the TSHr-Ab assay." (PMID 22654905, 2012). "Specific target proteins along the thyroid axis associated with autoimmune thyroid disease were evaluated in our study including thyroid-stimulating hormone receptor (TSH-R), 5′deiodinase, thyroid peroxidase, thyroglobulin, thyroxine-binding globulin, thyroxine, and triiodothyronine." (PMID 28894619, 2017). "In 2011, a large GWAS conducted by the China Consortium of the Genetics of Autoimmune Thyroid Disease in 1,536 individuals with GD and 1,516 controls confirmed TSHR as a primary susceptibility locus for GD by finding a robust association (OR = 1.35) of an intron 1 SNP (rs12101261) with the disease." (PMID 28421036, 2017). "The second mechanism by which TSHR intron 1 variants could trigger thyroid autoimmunity through defective central tolerance was initially proposed by Pujol-Borrell group." (PMID 28421036, 2017). "Furthermore, a human thyroid-stimulating hormone receptor mRNA variant encoding only the extracellular ligand-binding domain has also been found and reported to play a potential role in thyroid physiology and/or autoimmune thyroid disease." (PMID 25188337, 2014). "The thyroid-stimulating hormone receptor (TSHR) is a critical human autoantigen in autoimmune thyroid disease and the major regulator of the thyroid cell." (PMID 39483982, 2024). "GD is an autoimmune thyroid disease characterized by the presence of autoantibodies against the thyroid-stimulating hormone receptor (TSH-R), thyroglobulin and thyroperoxidase." (PMID 35309354, 2022). "Autoimmune thyroid disease is characterised by the generation of autoantibodies against self-antigens such as thyroid peroxidase, thyroglobulin, and thyroid-stimulating hormone receptor." (PMID 36705201, 2022). "The KEGG pathway enrichment analysis discerns that TSHR is enriched in various pathways including autoimmune thyroid disease (hsa05320), Thyroid hormone synthesis (hsa04918), and cAMP signaling pathway (hsa04024)." (PMID 33832456, 2021). "In a recent study, the determination of autoantibodies to TSHR presented helpful in the diagnosis and management of patients with autoimmune thyroid disease." (PMID 35140701, 2021). "This key observation resulted in development of the first in vitro receptor binding assay to measure TSHR autoantibodies (TRAb) to help in the diagnosis and management of autoimmune thyroid disease (AITD)." (PMID 32472423, 2020). "Measurement of TSHR autoantibodies (TRAbs) is helpful in diagnosis and management of autoimmune thyroid disease." (PMID 32472423, 2020). "Human MAbs to TSHR have been obtained from the peripheral lymphocytes of patients with autoimmune thyroid disease." (PMID 29849619, 2018). "The thyrotropin receptor (TSHR) is one of the primary antigens in autoimmune thyroid disease, being targeted by antigen-specific T cells and autoantibodies." (PMID 23691429, 2013). "With regard to autoimmune thyroiditis, which is the most frequent autoimmune endocrine disease, all major thyroid-specific antigens, i.e., thyroperoxydase, thyroglobulin, and thyrotropin receptor (TSHR), are also transcribed in human TECs in normal conditions." (PMID 24137108, 2013).
autoimmune thyroid disease (continued). "The presence of the TSHr-Ab as the only marker of thyroid autoimmunity has been described previously for a population of type 1 diabetes patients; however, GAD65-Abs were negative in our patients, and there is no need at present for insulin therapy." (PMID 22654905, 2012). "Thyroid function tests revealed elevated thyroid-stimulating hormone (TSH) with low T3 and low-normal free T4, serology was positive for anti-TPO and anti-TSHR antibodies, and ultrasound revealed features suggestive of thyroiditis, confirming autoimmune thyroid disease." (PMID 40861566, 2025). "In addition, it has been shown that some gut microbiota, such as Yersinia pestis and Helicobacter pylori, produce antigenic cross-reactive substances with the thyroid-stimulating hormone receptor, which affects thyroid autoimmunity." (PMID 39599685, 2024). "Additionally, the action of various cytokines in diabetes induces thyroid autoimmunity, and the combination of TRAb produced with the TSHR-α subunit prevents its conformation from changing, thus delaying its shedding, and the half-life of TSHR is prolonged." (PMID 34804362, 2021). "On the other hand, a mechanistic connection between autoimmune thyroid diseases and OLP has been suggested through the analysis of thyroid-stimulating hormone receptor (TSHR) expression in OLP patients." (PMID 41254953, 2025). "Genetic studies further confirm shared susceptibility, identifying overlapping loci between vitiligo and autoimmune thyroid disease, including immune regulatory genes and organ-specific targets such as TYR, TG, and TSHR." (PMID 41303876, 2025). "The predominant antigens involved in thyroid autoimmunity are thyroid peroxidase (TPO), thyroglobulin (Tg) and the TSH receptor (TSHR)." (PMID 39770919, 2024). "Candidate gene association studies and genome-wide linkage analysis identified nine loci involved in both vitiligo and autoimmune thyroid disease, including genes coding for tyrosine (TYR), thyroglobulin (Tg), and thyroid-stimulating hormone receptor (TSHR)." (PMID 35204408, 2022). "Thyroid autoimmunity involves a breakdown in self-tolerance to three thyroid proteins: thyroglobulin, thyroid peroxidase (TPO), and the thyroid-stimulating hormone receptor (TSHR)." (PMID 28620373, 2017). "Autoimmune thyroid diseases are usually accompanied by the presence of anti-thyroid peroxidase (TPO), anti-thyroglobulin (Tg), and anti-thyroid-stimulating hormone receptor (TSHR) antibodies." (PMID 28536577, 2017). "The absence of TSHR expression on NKT cells in both AITD and non-AITD patients suggests that NKT cells do not participate directly in the TSHR-mediated pathways involved in thyroid autoimmunity." (PMID 39518994, 2024). "Autoimmune thyroid diseases (AITD) are signified by the presence of anti-thyroid peroxidase (TPOAb), anti-thyroglobulin (TgAb), and thyroid-stimulating immunoglobulin (TSI) directed to TSH receptor (TSHR)." (PMID 39685923, 2024). "Evidence for original antigenic sin in spontaneous thyroid autoimmunity is revealed by autoantibody interactions with immunodominant regions on thyroid autoantigens, thyroglobulin (Tg), thyroid peroxidase (TPO), and the thyrotropin receptor (TSHR) A-subunit." (PMID 29326719, 2017). "Thyrotropin receptor autoantibodies (TRAb), or thyroid stimulating hormone receptor (TSHR) autoantibodies, play a critical role in autoimmune thyroid disease and are classified as stimulating, blocking, or neutral (although the latter has been shown to modulate downstream TSHR signaling)." (PMID 28184292, 2017). "Unlike multiple sclerosis or EAE, original antigenic sin appears to be characteristic of thyroid autoimmunity as reflected by the recognition of an autoantibody IDR in humans and in the response of transgenic hTSHR/NOD.H2h4 mice to injection with inappropriate TSHR antigen." (PMID 29326719, 2017).